WNT5A (Wnt family member 5A)
Diseases named in the same sentence as WNT5A in open-access papers (continued):
Sharing a sentence is not in itself a finding about the gene and the disease.
melanoma (continued). "In melanoma, Wnt-5a was shown to increase protein kinase C (PKC) activity and MMP secretion and, thus, enhance invasiveness in an independent manner from β-catenin-mediated-transcription." (PMID 39766864, 2024). "Exogenous Wnt5a interventions, for instance, increase the expression of vimentin, snail, and other interstitial markers of melanoma cells, which promotes melanoma metastasis." (PMID 38898476, 2024). "Wnt5a-induced depalmitoylation of melanoma cell adhesion molecules (MCAM) promoted melanoma cell invasion ability." (PMID 38315203, 2024). "Aged lung microenvironment enables melanoma cells to enter dormancy and efficiently initiate metastatic outgrowth in the lungs by inhibiting WNT5A." (PMID 38730468, 2024). "In a BRAFV600E/PTEN−/− melanoma model, the inhibition of PD-1 increases CD8+ T-cell activity and IFN-γ secretion, which, in turn, increases Wnt5a expression in melanoma cells." (PMID 38893071, 2024). "Co-culture experiments demonstrate that blocking Wnt5a expression leads to endothelial cell morphological defects, whereas expressing Wnt5a in endothelial cells induces exosomes release from melanoma cells." (PMID 39850798, 2024). "On molecular level, blocking of TGF-β in a melanoma in vitro model results in a GLI2low/MITFhigh phenotype, which in turn leads to reduced WNT5A expression and to less invasive capacities." (PMID 38419052, 2024). "EZH2 was reported to mediate PGC1α gene silencing, thereby increasing WNT5A expression and promoting migration and metastasis in melanoma." (PMID 38566211, 2024). "The overexpression of Wnt5a in melanoma has a positive correlation with the angiogenic marker ESAM during gene analysis impacting the degree of branching in endothelial cells." (PMID 38243280, 2024). "As expected, we observed strong induction of some Wnts, whereas others, such as Wnt5a and Wnt5b, which were upregulated in several melanoma cell lines, were surprisingly downregulated in the analyzed melanoma cell lines compared to those in NHEMs." (PMID 38388496, 2024). "For instance, while Wnt-5a generally inhibits Wnt signaling, it also enhances invasiveness in melanoma cells." (PMID 39766864, 2024). "Klotho protein decreases melanoma cell invasive potential by negatively regulating Wnt5A-mediated FLNA cleavage." (PMID 39195282, 2024). "In the endogenous WNT5A low expressed melanoma cells, the stimulation with rWNT5A led to a great release of EVs carrying the immunoregulatory cytokine IL-6, and more important the pro-angiogenic agents, including IL-8, VEGF and MMP2." (PMID 37575250, 2023). "The ROR2 ligand WNT5A was also overexpressed in BRAFMut melanomas, and in ROR2-overexpressing BRAFV600E cells MEK inhibition downregulated WNT5A and VEGF secretion." (PMID 36539575, 2023). "Studies have shown that WNT5A regulates IL-6 expression in melanoma and modulates the expression of SASP factors in tendon stem cells, and that IL-6 exhibits a reciprocal regulation with CCL2 in non–small cell lung cancer." (PMID 37607007, 2023). "As an atypical Wnt signaling, WNT5A can promote the spread to distant tissues or organs and the formation of metastatic foci of melanoma, whereas the high expression of WNT5A commonly predicted a poor prognosis in melanoma patients." (PMID 37575250, 2023). "A recent study showed that WNT5A initially supports the dissemination and seeding of melanoma cells in the lungs, activating dormancy." (PMID 37607007, 2023). "For instance, knockdown of WNT5A in melanoma xenografts in mice resulted in a in a lower number of Foxp3+ regulatory T cells (Treg) in the tumors as well as in tumor-draining lymph nodes." (PMID 36982422, 2023).
melanoma (continued). "While best characterised in bone marrow, similar research has shown Wnt5a to reduce cell cycling of melanoma metastases in the lung microenvironment, accompanied by elevated p21 expression, and delayed metastatic outgrowth." (PMID 37608096, 2023). "Consistently, overexpression of WNT5A in melanoma cell lines downregulated the expression of MART-1, which was shown to be dependent on a PKC-STAT3 signaling axis." (PMID 36982422, 2023). "It has also been shown that filopodia formation mediated by ROR2 is required for WNT5A-induced cell migration in human melanoma cell lines further supporting our observation of a role for direct transport of ROR2 in inducing migration in AGS cells." (PMID 37722040, 2023). "The tumor-promoting role of WNT5A was further supported by the observed correlation between WNT5A expression in primary melanoma tissue and reduced metastasis-free survival." (PMID 36551563, 2022). "We reduced the expression of WNT5A by transiently transfecting BRAFi-sensitive and BRAFi-R2 melanoma cells with two independent WNT5A-targeting siRNA oligonucleotides." (PMID 36551563, 2022). "The positive effects of Wnt5a on melanoma metastasis also include Ca2+-dependent exosome release, containing the pro-angiogenic and immunosuppressive factors (VEGF, IL-6, and MMP-2), which suppresses endothelial cell branching." (PMID 35162934, 2022). "On the other hand, high WNT5a expression in melanoma or gastric cancer correlates with poor prognosis." (PMID 36612190, 2022). "WNT5A-dependent signaling promotes the resistance of melanoma cells to BRAFi via its receptors RYK and FZD7 and the activation of PI3K/AKT signaling has also been reported." (PMID 36181568, 2022). "Wnt5a was found to be expressed in highly aggressive melanoma and was able to increase melanoma invasive potential by activating PKC and raising [Ca2+]i in a transfected model." (PMID 35162934, 2022). "Wnt5a leads to the remodeling of the cytoskeleton and increases melanoma motility by activating calpain-1, leading to the cleavage of filamin A." (PMID 35162934, 2022). "Gene expression profiling initially identified that WNT5A expression correlated with cell motility and invasiveness of human melanoma cells." (PMID 36620565, 2022). "The reciprocal antagonism between MITF and Wnt5A can also control the dynamic phenotype switching in melanoma cells." (PMID 35406721, 2022). "Previously, we have shown that MARCKS activation is required for WNT5A-induced invasion of BRAFi-sensitive, melanoma cells." (PMID 36551563, 2022). "Previously, we showed that combined inhibition of elevated WNT5A and IL-6 signaling reduced the invasion and migration of BRAFi-resistant (BRAFi-R) melanoma cells." (PMID 36551563, 2022). "Numerous studies now identify aberrations in β-catenin-independent WNT pathways in melanoma, most notably activated by WNT5A." (PMID 36181568, 2022). "This is consistent with previous results indicating that Wnt5A expression increases in old (55–65 years old) melanoma patients compared to young (25–35 years old) patients." (PMID 36135194, 2022). "H3K27me3-mediated PGC1α gene silencing promotes melanoma invasive phenotype through TCF12/WNT5A/YAP axis." (PMID 35406721, 2022). "Wnt5A has been reported to suppress the adaptive immune response of CD8 T cells in melanoma through metabolic programming." (PMID 36091060, 2022). "Here, we found that substantial increases in the levels of MARCKS expression and activating phosphorylation were correlated with elevated WNT5A expression and increased invasion and migration of BRAFi-R melanoma cells." (PMID 36551563, 2022). "Several studies reported that WNT5A was upregulated in breast carcinomas, prostate carcinomas, and melanoma, indicating its oncogenic role in these cancers." (PMID 35595735, 2022).
melanoma (continued). "Recently, we showed that the WNT5A/PKC pathway regulates BRAFi-sensitive melanoma cell invasion at least in part by its downstream activation of the protein myristoylated alanine-rich protein c-kinase substrate (MARCKS)." (PMID 36551563, 2022). "We found that a combined treatment with relatively high concentrations of the WNT5A antagonist Box5 and the IL-6 blocking antibody resulted in approximately 50% inhibition of BRAFi-R melanoma cell invasiveness." (PMID 36551563, 2022). "For example, melanoma and gastric cancer cells acquired increased migration and metastasis while Wnt5a was overexpressed." (PMID 36273233, 2022). "Taken together, our results suggest that low WNT5A signaling in melanoma cells promotes a rounded amoeboid type of invasion, which quite likely serves as a compensatory response to decreased WNT5A/Cdc42‐driven invasion." (PMID 33969605, 2021). "In line with our findings here, it has been reported that Wnt5A/FZD-5 signaling increased melanoma cell adhesion and migration, which was reversed in the presence of Box537,39." (PMID 33723319, 2021). "This phenomenon partially explains the enduring melanoma cell invasion observed after impaired WNT5A signaling and has therapeutic implications." (PMID 33969605, 2021). "Taken together, our results suggest that WNT5A downregulation inhibits Cdc42‐dependent melanoma cell invasion in 3D collagen matrices." (PMID 33969605, 2021). "WNT5A knockdown impaired Rho GTPase Cdc42 activity, resulting in reduced invasion of amoeboid and mesenchymal melanoma cells." (PMID 33969605, 2021). "A similar Wnt5a distribution was found in melanoma cells cultured with delipidized serum, which limits fatty acid uptake." (PMID 37849907, 2021). "All these assays strongly support the conclusion that RNF43 acts as a strong molecular inhibitor of WNT5A-triggered proinvasive features of melanoma." (PMID 34702444, 2021). "In vitro studies have shown that the ligand WNT5A plays an essential role in regulating and promoting the invasive migration of melanoma cells." (PMID 33969605, 2021). "For example, Wnt5a plays a pro-tumorigenic role in gastric cancer, non-small cell lung cancer and melanoma, in contrast to thyroid and colorectal cancer." (PMID 33754039, 2021). "This is applicable to the present study, in which we found that inhibition of RhoA signaling by the RhoA‐GEF inhibitor Rhosin in WNT5A‐deficient melanoma cells resulted in an even more significant reduction in melanoma cell invasion than WNT5A knockdown alone." (PMID 33969605, 2021). "Here, we show that impaired WNT5A signaling not only significantly decreases melanoma cell invasion but can also promote a more rounded, amoeboid invasive phenotype." (PMID 33969605, 2021). "Knockdown of WNT5A expression not only decreased melanoma cell invasion but also resulted in a significant reduction in Cdc42 activity but no change in Rac1 activity in either cell line." (PMID 33969605, 2021). "Further, we show that RNF43 is a relevant inhibitor of pro-metastatic WNT5A signaling in melanoma where it prevents both WNT5A-induced invasive behavior and WNT5A-assisted development of resistance to B-RAF and MEK inhibitors." (PMID 34702444, 2021). "WNT5A signaling has been related to numerous biological features that support the invasive properties of melanoma." (PMID 34702444, 2021). "Our results suggest that dual targeting of WNT5A and RhoA signaling is a more effective strategy for controlling the invasion of BRAF wild‐type and BRAFV600 mutated melanomas treated with a BRAF inhibitor than targeting either of the proteins individually." (PMID 33969605, 2021). "Along with beta 3 integrin and WNT5A, syndecan-4 is part of a gene signature characteristic for metastatic disease in melanoma." (PMID 33810567, 2021). "We demonstrate that the newly characterized RNF43-WNT5A regulatory module controls WNT5A signaling and biology in melanoma." (PMID 34702444, 2021).
melanoma (continued). "The clinical importance of WNT5A is highlighted by previous results revealing increased expression of WNT5A at both the mRNA and protein levels in clinical melanoma samples compared to normal samples, suggesting that WNT5A promotes melanoma progression." (PMID 33969605, 2021). "In melanoma, a number of these downstream signaling pathways have been shown to be involved in WNT5A‐dependent cell migration and invasion." (PMID 33969605, 2021). "WNT5A is differentially expressed during various stages of melanoma, exhibiting a limited increase in expression during benign nevus and the vertical growth phase and a greater increase in expression during the metastatic phase." (PMID 33969605, 2021). "There is a striking difference in migration mode between HTB63 and WM852 melanoma cells that correlates with their different levels of WNT5A expression." (PMID 33969605, 2021). "Signaling cascade activated by WNT5A in melanoma drives epithelial–mesenchymal transition-like program (EMT), resulting in increased metastatic properties of melanoma cells in vitro and in vivo." (PMID 34702444, 2021). "It was shown that murine Ror2 contributed to migration and metastasis and that ROR2 expression associates with a more invasive phenotype and is necessary for the Wnt5A-mediated metastasis of melanoma cells." (PMID 34774050, 2021). "MDSCs drive melanoma cells to the invasive state, at least in part, via their secretion of WNT5A, which in turn increases pro-inflammatory cytokine secretion by tumor cells and facilitates MDSC recruitment and function." (PMID 34604096, 2021). "In the present study, we analyzed how WNT5A expression and signaling relate to phenotypic changes and the invasiveness of melanoma cells." (PMID 33969605, 2021). "The results suggest that dual targeting of WNT5A and RhoA activity is a more efficient approach to impair melanoma cell invasion than inhibiting each target alone." (PMID 33969605, 2021). "Another early study showed that a pan-PKC inhibitor, Gö 6983, blocked WNT5A-mediated melanoma dedifferentiation in vitro, with increased expression of PAX3 and melan-A." (PMID 34604096, 2021). "IL-6 increases the invasiveness and motility of melanoma cells through the MAPK pathway which upregulates WNT5A, which is a major regulator of phenotype switching." (PMID 34604096, 2021). "RNF43 inhibits responses to WNT5A, which results in the suppression of invasive properties of melanoma cells." (PMID 34702444, 2021). "We found that melanoma cell invasion, which had been inhibited by WNT5A knockdown in both cell lines, was restored in these cells by the addition of this activator (striped columns)." (PMID 33969605, 2021). "We next found that dual targeting of WNT5A and RhoA more effectively reduced melanoma cell invasion than targeting either protein individually." (PMID 33969605, 2021). "Here, we investigate how WNT5A signaling, a tumor promotor in melanoma, relates to Rho GTPase activity and amoeboid migration." (PMID 33969605, 2021). "These activities of RNF43 are physiologically relevant and block pro-metastatic WNT5A signaling in melanoma." (PMID 34702444, 2021). "(E, E′, E′′) Culture media from melanoma A375, A375 IV, and A2058 cell lines were collected after 48 hr and analyzed by western blotting for the presence of WNT5A (E′) and WNT11 (E′′)." (PMID 34702444, 2021). "Among those mechanisms, WNT5A signaling has a prominent role – WNT5A expression was shown to positively correlate with vemurafenib resistance and WNT5A treatment decreased melanoma cells’ response to the vemurafenib." (PMID 34702444, 2021). "We found that reduced WNT5A signaling significantly inhibits Cdc42 activity and melanoma cell invasion in a spheroid invasion assay." (PMID 33969605, 2021). "The main aim of this study was to analyze the potential role of WNT5A in melanoma cell plasticity, in particular mesenchymal‐to‐amoeboid transition." (PMID 33969605, 2021).
melanoma (continued). "Here, we show that this effect can be reversed by inhibiting the lipidation of endogenous WNT ligands in melanoma cells, which naturally produce a lot of endogenous WNT5A." (PMID 34406391, 2021). "In the COX models, we recruited two known prognostic biomarkers of melanoma, S100B, and WNT5A, to better identify the prognostic value of the hub genes." (PMID 32934956, 2020). "Treatment of melanoma cells with media of aged fibroblasts results in increased Wnt5a expression and less KL mRNA expression, compared to incubation with media of young fibroblasts." (PMID 33520985, 2020). "As expected, our invasion assay revealed that WNT5A silencing decreased the invasive capacity of HTB63 melanoma cells." (PMID 32033033, 2020). "Previous studies have shown that multiple genes in melanoma cells, such as Wnt5a, MELK, and PTX3, can trigger the NFκB signaling pathway, thereby migrating and invading melanoma." (PMID 33679872, 2020). "In this study, we identified MARCKS phosphorylation as a novel WNT5A downstream signal crucial for melanoma cell invasion, a key event in the metastatic process." (PMID 32033033, 2020). "Although WNT5A/PKC signaling has been previously reported to promote melanoma cell migration and invasion resulting in increased metastasis, a functional role of the PKC substrate MARCKS has not been studied." (PMID 32033033, 2020). "Most importantly, the presence of the MARCKS phosphorylation inhibitory peptide MANS abolished WNT5A-induced A2058 melanoma cell invasion." (PMID 32033033, 2020). "Previous studies have revealed the elevated Wnt5a expression in more advanced and aggressive disease in patients with melanoma 33, gastric cancer, lung cancer 34 and prostate cancer." (PMID 32742496, 2020). "We silenced WNT5A in HTB63 melanoma cells with two different WNT5A siRNAs and observed that there was only a minor effect on the total MARCKS level." (PMID 32033033, 2020). "Several of these mechanisms have been investigated in melanoma and the results revealed that WNT5A exerts a dichotomous role in melanoma." (PMID 32659938, 2020). "Our study demonstrates multiple novel findings outlining an essential role of MARCKS phosphorylation in WNT5A-induced melanoma cell invasion." (PMID 32033033, 2020). "Several different regulators, including WNT5A and their complex downstream signaling pathways, have been identified to control various aspects of melanoma metastasis." (PMID 32033033, 2020). "For example, Wnt3a and Wnt5a are expressed at higher levels in melanoma, whereas Wnt1 is highly expressed in lung adenocarcinoma." (PMID 32132993, 2020). "Klotho can inhibit internalization and signaling of Wnt5A, which drives melanoma metastasis and resistance to targeted therapy." (PMID 33373316, 2020). "The finding that MARCKS expression relates to the progression of melanoma is comparable to that found for WNT5A expression in relation to melanoma progression." (PMID 32033033, 2020). "In different melanoma cell lines, a mutually inhibitory effect of Wnt5a and KL expression is established impacting on metastasis." (PMID 33520985, 2020). "Melanoma cells exerting a high level of WNT5A when exposed to vemurafenib treatment or other stress, developed a sort of drug resistant state (pseudosenescence), still retaining invasive capacity and the ability to form metastases." (PMID 32659938, 2020). "It has been shown in both murine and human models that Wnt5a from melanomas affects the local DCs to express indoleamine 2,3-dioxygenase-1 (IDO1) that stimulates development of T regulatory cells (TRegs) through kynurenine." (PMID 32292402, 2020). "Our results demonstrate that WNT5A-induced activation of MARCKS is a necessary molecular event that is crucial for the metastatic behavior of melanoma cells." (PMID 32033033, 2020). "The aim of the present study was to investigate a potential downstream regulatory role of the MARCKS protein in WNT5A-mediated invasion of melanoma cells." (PMID 32033033, 2020).